B2M (beta-2-microglobulin)
Diseases named in the same sentence as B2M in open-access papers (continued):
Sharing a sentence is not in itself a finding about the gene and the disease.
infection (continued). "Some genes related to the inflammatory response, such as Cxcl10, Clu and antigen presentation, such as B2m, Fcer1g showed over-expression only at 72 and 96 hr post infection." (PMID 18558011, 2008). "The fact that virus internalization was diminished and/or delayed in B2M-deficient cells does not preclude additional effects later in infection." (PMID 36574441, 2022). "For that, purified VV particles were incubated with soluble B2M and then used for infection." (PMID 36574441, 2022). "The instability of B2M was induced by infection, which may reflect its role in antigen binding and presentation by the major histocompatibility complex (MHC), hence its limitation as a reference gene in such studies." (PMID 28182746, 2017). "Genes like B2m, Mst1, Igsf1, Ifitm3 and Nt5c2 were found to be upregulated whereas genes like Fyb, Ilf3, Wnt4 and Socs3 were found to be downregulated in the brain against both V3000 and V3034 infections." (PMID 28446152, 2017). "Moreover, CD8+ cells appear to be important for the early containment of bacteria within the intestines; the spleens and livers of B2m−/− neonates were heavily colonized by bacteria as early as 48 h post infection." (PMID 28119902, 2016). "Interestingly, all NK cell-depleted B2m-/- mice succumbed to the infection as well (***p = 0.0015), indicating a direct role for MHC-I-unlicensed NK cells in controlling influenza virus infection in these mice." (PMID 26928844, 2016). "MHC class I receptors such as Cd1d1, B2m and Ap3d1 were also upregulated at 96 hr post infection." (PMID 18558011, 2008). "A decrease in the abundance of this protein may indicate a reduction in antigen‐presenting processes in the burn cohort, or that there was increased relative B2M abundance in the control group, who were recruited from a childcare setting, where infection is known to be increased." (PMID 39895030, 2025). "MA10 infection induced six down-regulated (Pllp, Malat1, Myrf, Mag, Ptgds, Ugt8a) and two upregulated DEGs (Sgk1, Mbp), while Aβ pathology resulted in one down-regulated (Hmgb1) and ten up-regulated DEGs (Apoe, B2m, Clu, Cstd, Gfap, Psen1, Pllp, Cst7, Cd9, Plp1)." (PMID 41497643, 2025). "Therefore, we speculated that this protein plays an important immune function in the infection process, and that the interaction between p72 and B2M may affect this process." (PMID 38481793, 2024). "Therefore, we can infer that an increased dose of B2M at pH 4.5 mediates the formation of fibrils and may thus contribute to the AMP effect; infection is typically associated with a low pH environment." (PMID 34199259, 2021). "However, 100% of the B2m−/− mice previously infected as neonates survived the infection." (PMID 28119902, 2016). "Regarding the mRNA expression, a significant increase in TGF-β1, HIF-1α, NGAL, B2M, FGF23, TLR-2, IL-18, and YKL-40 was observed in the long-term post-MHV-1 infection, whereas only NGAL was found to be significantly increased in the acute stage post-infection." (PMID 37626956, 2023). "Virus entry was significantly reduced as a result of B2M inactivation, both in HeLa and HAP1 cells, indicating that inhibition of infection occurs at an early stage in the virus cycle, before the start of DNA replication." (PMID 36574441, 2022). "Genes related to antigen presentation, such as components of MHC I complex-B2M and multiple MHC Ia antigens, tapasins, and proteasome components, were also activated during the infection." (PMID 35215144, 2022). "Changes in gene expression in the brains of infected animals is minimal at 2- and 4-days post infection with moderate increases in Interferon-inducible CXCL10, CXCL11, B2m, and STAT1, as well as pro-inflammatory TNF, IL-1b and C3." (PMID 32133008, 2020). "MYXV infection induces no significant changes in MHC class I expression on MSCs between constitutive expression of the β-2 microglobulin (B2M) gene in MYXV-infected and mock-infected MSCs 24 h post-infection (p.i.)(p = 0.0596)." (PMID 32775618, 2020).
infection (continued). "The majority of genes (CANX, B2M, CD74 and CTSB) in Antigen processing and presentation pathway were downregulated during infection." (PMID 33177569, 2020). "To investigate if the interaction between STING and FP represented a strategy for IAV to evade STING-dependent induction of interferon production we pretreated THP-1-derived B2M and STING knock-out (KO) cells with FP before infection with IAV." (PMID 26893169, 2016). "We determined the mRNA expression levels of several housekeeping genes (GAPDH, B2M, HPRT1) to examine the effect of infection with H6R28LEP on PBMCs." (PMID 23409116, 2013). "The transcript abundance of B2M, MHC class I antigen 2 (SLA-2), SLA-3, TAP2, and chaperones (such as GRP78) was markedly increased after infection with N-PRRSV while the transcript abundance of SLA-B was significantly decreased." (PMID 20614006, 2010). "Further, the combination including four validated indexes and two classical infection indexes for septic diagnosis had the highest AUC‐ROC of 0.772, which was significantly better than that of ApoC3, VCAM1, and ApoE respectively, besides B2M." (PMID 34825737, 2022). "As a control, infected and uninfected MHC-I-deficient mice (B2m-/- mice) were included, and as expected, displayed no increase in MHC-I staining upon infection." (PMID 26928844, 2016). "The four top ranked genes, from either selection method after exclusion of the differentially expressed B2M, were used to normalise the measurements of the remaining six candidate transcripts, as well as IL-8 and TGFB transcripts, in the fibroblast infection dataset." (PMID 27537060, 2016). "At this point, there is no clear mechanism to account for B2M role during infection." (PMID 36574441, 2022). "Finally, it is important to note that B2M is not a good tool to discriminate between infection and other forms of inflammation." (PMID 31063510, 2019). "At 2 days after infection, EBV markedly induced expression of MYC, CD21, CD23, HES1, and BATF (positive controls) 10- to 20-fold, possibly through EBNA2; in contrast, host housekeeping genes including β-2 microglobulin (B2M) and RNA polymerase II (POLR2A) were unaffected." (PMID 30487153, 2018). "Infections of N-PRRSV viruses resulted in fever and inflammatory response, as indicated by high expression of proinflammatory cytokines and chemokines, adhesion molecules, inflammatory enzymes and receptors, such as IL-1β, IL8, SELL, ICAM, CCL2, CXCL9, CXCL10, B2M, proteasomes, cathepsins." (PMID 20614006, 2010). "Furthermore, increased levels of TAP-transporters (TAP1, TAP2), MHC I components B2M and HLAs, together with the ER chaperons calreticulin (CALR) and calnexin (CALN), and aminopeptidases ERAP1 and ERAP2 indicated upregulation of MHC I dependent antigen presentation with progressing infection." (PMID 37112941, 2023). "In contrast, beta-2-microglobulin (B2M) was slightly upregulated in MP12 and ZH548 infected cells at 18 hpi and glucuronidase beta (GUSB) was not altered after infection." (PMID 29085037, 2017). "The reference genes B2M and/or GUSB were selected since their expression did not change significantly following infection." (PMID 27978534, 2016).
kidney disease (20 papers, 2014 to 2025). "Dosage of beta 2-microglobulin, a marker of tubule damage, has been used to identify early patients who are at increased risk of kidney disease." (PMID 31430930, 2019). "Plasma and serum elevations of B2M were found to be associated with a plethora of pathological conditions including renal diseases and cardiovascular diseases." (PMID 26431327, 2015). "This study will provide important data about the local epidemiology of kidney disease in a high-risk rural setting and the utility of emerging renal filtration markers (Beta 2 Microglobulin and Cystatin C), while generating data and methods for the analyses of microRNA biomarkers." (PMID 29486722, 2018). "Beta-2 microglobulin is an indicator of renal tubular function that is frequently used to assess kidney disease and the effectiveness of kidney transplants." (PMID 37775738, 2023). "In the case of renal tubular injury, the concentration of beta-2 microglobulin increases, making it a useful marker for kidney disease." (PMID 37775738, 2023). "Some candidate biomarkers for kidney disease also exhibited high variations, such as beta-2-microglobulin (1.26), zinc alpha-2-glycoprotein (0.98) and alpha-2-HS-glycoprotein (0.84)." (PMID 26222143, 2015). "Increased levels of B2M in urine are indicative of early proximal tubular dysfunction and show a significant correlation between plasma and urine concentrations, as well as the progression of renal disease in patients with FD." (PMID 39408658, 2024). "Notably, among these abnormally expressed proteins, 19 proteins were reported as kidney disease markers (Ada, Ambp, Anxa1, B2m, Camp, Col1a1, Cp, Ggt1, Glb1, Lgfbp7, Lifr, Lpl, Plau, Ptgds, S100a8, Serpinc1, Serpina3k, Tff1, and Vtn) (highlight in green)." (PMID 31708494, 2019).
cardiovascular disease (13 papers, 2010 to 2025). "Plasma B2M is a clinical biomarker associated with cardiovascular disease, kidney function, and inflammation." (PMID 30669119, 2019). "B2M, a risk marker for cardiovascular disease, was found within this cluster." (PMID 37769126, 2023). "However, the association between B2M and cardiovascular disease remains under-researched." (PMID 28249620, 2017). "GrimAge is based on seven plasma protein levels related to various diseases and conditions, including cardiovascular disease (Plasma B2M) and cognitive functions (Plasma B2M, ADM, Cystatin C, and leptin)." (PMID 40699219, 2025). "Although serum B2M have been proved to be a predictor of cardiovascular disease and mortality in dialysis patients, our findings cannot verify the harmful effect of serum B2M per se in cognitive function." (PMID 31643008, 2020).
neurodegenerative disease (7 papers, 2019 to 2025). A disorder of the central nervous system characterized by gradual and progressive loss of neural tissue and neurologic function. "Evidence suggests that B2M has a strong association with complex neurodegenerative diseases such as Alzheimer’s and Parkinson’s disease." (PMID 33398051, 2021). "Increased plasma B2M results in deposition of amyloid fibrils, which is associated with over 20 degenerative diseases, including AD." (PMID 31333395, 2019).
hematological malignancies (6 papers, 2014 to 2025). "At present, serum B2M levels have been extensively studied for their prognostic value in a variety of hematologic disorders." (PMID 38562177, 2024). "The serum level of B2M has been established as a prognostic marker in hematologic disorders, solid organ neoplasms, and rheumatic autoimmune diseases (Sjogren’s syndrome, systemic lupus erythematosus, rheumatoid arthritis)." (PMID 39795957, 2024).
bacterial infection (4 papers, 2021 to 2025). "The beta 2 microglobulin (B2m) gene can form amyloid fibers and can also prevent bacterial infection." (PMID 36834981, 2023). "Thus, sB2M-9 is suggested to exhibit early lymphocyte recruitment in the milieu of REC with bacterial infection, in addition to the classic B2M-restricted mechanism; moreover, it may be responsible for resistance to tuberculosis in the lungs." (PMID 34199259, 2021). "The expression of B2m, Ctsl, Calr, and Pdia3 suggests efficient antigen processing and presentation process, and the upregulation of Rac1, and Cd14 indicats the involvement of TLR2 and TLR4, which are essential for Th1/Th17 responses elicited by wPVs or bacterial infection." (PMID 34759909, 2021).
benign neoplasm (3 papers, 2016 to 2021). A neoplasm which is characterized by the absence of morphologic features associated with malignancy (severe cytologic atypia, tumor cell necrosis, and high mitotic rate). "Our HLA-A/B/C and B2M staining results and the associated CTL Target Score calculations suggest that plexiform and nodular benign tumors and MPNST demonstrate similar capacity to present tumoral antigens to CTLs, while diffuse histology tumors may not." (PMID 29137242, 2017). "Current study did not test the serum level of B2M due to the lack of serum collection before or after surgery, but previous study has shown that the serum and peritoneal fluid of B2M was significant higher in patients with OC than in patients with benign neoplasms." (PMID 26983758, 2016). "Among the benign tumors sampled from this patient, CTL Target Scores rose over time, reflecting increases in both the HLA-A/B/C and B2M staining scores." (PMID 29137242, 2017).
metabolic disorders (3 papers, 2013 to 2025). "Therefore, we propose that an HFD induces iron overload and ferroptosis in hypertrophic adipocytes through B2M-involved iron transport mechanisms, potentially releasing certain DAMPs that induce M1 polarization, exacerbating adipose inflammation and metabolic disorders." (PMID 41330906, 2025).
brain disease (2 papers, 2016 to 2024). "Pathway analysis of the 34 peptides underlined the role of viral entry in fetuses with severe brain disease as well as the potential importance of both beta-2-microglobulin and adiponectin to protect the injured fetal brain infected with CMV." (PMID 26808779, 2016). "Among them, 8 differential urinary proteins were previously reported to be closely associated with brain disease, including NP, FZD1, B2M, EPCR, ATRN, MB, CA1and VPS4A." (PMID 38836960, 2024). "The question of whether B2M exerts a beneficial or detrimental impact in the context of brain diseases remains a subject of controversy." (PMID 38836960, 2024).
hematologic cancer (2 papers, 2023 to 2025). "The authors also suggested a significant association between serum B2M and mortality from total, lung, and hematological cancers." (PMID 37510802, 2023). "Knockout of antigen-presenting genes, including MHC-I and B2M, enhances the sensitivity of across hematologic cancer cell lines to NK cells, supporting the “missing-self” mechanism of NK cell activation." (PMID 40191187, 2025).
kidney (2 papers, 2021 to 2024). "Our data suggest retinol-binding protein (RBP4), beta-2-microglobulin (B2M), cystatin-C (CST3), hepcidin (HAMP), and fatty acid-binding protein (L-FABP) hold promise as candidates for kidney damage surveillance in Bothrops envenoming." (PMID 38536893, 2024).
bone disorder (1 paper, 2024). "Dialysis-related amyloidosis, caused by the accumulation of beta-2 microglobulin, underscores the long-term complications associated with hemodialysis, manifesting in joint and bone disorders that impair patient mobility and quality of life." (PMID 39493712, 2024).
peripheral neuropathies (1 paper, 2025). "Future studies incorporating protein-level validation, functional assays, and regenerative models will be essential to evaluate the therapeutic potential of modulating B2M-dependent signaling in peripheral neuropathies." (PMID 40700124, 2025).
respiratory diseases (1 paper, 2025). "Beta-2-microglobulin (B2M) is a component of the major histocompatibility complex class I and is involved in the pathogenesis of respiratory diseases." (PMID 40778772, 2025).
B2M also shares sentences with these, for which no sentence is quoted: head and neck squamous cell carcinoma (5 papers); heart failure (5); Chronic Lymphocytic Leukemia (4); hepatocellular carcinoma (4); Neurological Disease (4); systemic lupus erythematosus (4); adenocarcinoma (3); age (3); esophageal cancer (3); infectious disease (3); uveal melanoma (3); AA amyloidosis (2); acute coronary syndrome (2); autism (2); colon (2); end-stage renal disease (2); endometrial cancer (2); Hepatitis (2); Hyponatremia (2); hypophosphatemia (2); inflammation (2); leiomyosarcoma (2); liposarcoma (2); MALT lymphoma (2); myelodysplastic syndrome (2); myocardial inflammation (2); neutropenia (2); non-small cell lung carcinoma (2); pancreatic ductal adenocarcinoma (2); plasmacytoma (2).
A further 107 diseases each share a sentence with B2M in 2 papers or fewer.